IDH1 (isocitrate dehydrogenase (NADP(+)) 1)
Diseases named in the same sentence as IDH1 in open-access papers (continued):
Sharing a sentence is not in itself a finding about the gene and the disease.
chondrosarcoma (continued). "In our study, we aimed to demonstrate that AGI-5198 would have similar effects on IDH1-mutant human chondrosarcoma cell lines JJ012 and HT1080." (PMID 26368816, 2015). "In contrast to the persistent presence of IDH1 mutations throughout tumour progression, p16/CDKN2A copy number variation only occurred in high grade chondrosarcomas (GII, GIII or dedifferentiated neoplasms)." (PMID 25432631, 2015). "We sought to determine if treatment with AGI-5198 would similarly inhibit tumorigenic activity and D-2HG production in IDH1-mutant human chondrosarcoma cells." (PMID 26368816, 2015). "Our data supports that D-2HG is likely to serve as a biomarker for mutant IDH activity in chondrosarcomas, and supports additional investigation of mutant IDH1 inhibition as a treatment strategy in patients with unresectable disease." (PMID 26368816, 2015). "The investigation into AGI-5198-mediated changes in gene expression, epigenetics and differentiation of IDH-1 mutant chondrosarcoma cell lines is ongoing in our laboratory." (PMID 26368816, 2015). "There is no published information regarding the effects of this compound on IDH1-mutant chondrosarcoma cells." (PMID 26368816, 2015). "To assess the role of mutant IDH1 in chondrosarcoma cell proliferation, we incubated the cell lines with the IDH1 mutant inhibitor AGI-5198 for 72 hours." (PMID 25895133, 2015). "The p16/CDKN2A copy number variation occurs in at least 50 % of IDH1 mutant-bearing high grade chondrosarcomas, and the findings support the concept that the p16/CDKN2A alterations are likely to be associated with disease progression." (PMID 25432631, 2015). "Although IDH1/IDH2 mutations appear to be an important genetic event in the pathogenesis of enchondromas and central chondrosarcomas, other mutations are likely to exert an impact on the biological behaviour of the disease." (PMID 25432631, 2015). "Even though it is well known that prolonged culturing affects global methylation levels in cell lines, we were able to show a different methylome in IDH1/2 mutant and IDH1/2 wildtype chondrosarcoma cell lines." (PMID 25895133, 2015). "Although inhibition of mutant IDH1 decreased levels of D-2-HG up to 90%, only one out of three IDH1 mutant chondrosarcoma cell lines (JJ012) showed a minor effect on viability." (PMID 25895133, 2015). "Recently IDH1 and IDH2 mutations were found in conventional central and dedifferentiated chondrosarcomas." (PMID 22928481, 2012). "Our study posits that initiating driver mutations in IDH1 or IDH2 in cartilaginous tumors are not required for the persistence of chondrosarcoma." (PMID 41299743, 2025). "Hypermethylated pathways in IDH1 R132Q-versus R132H-expressing chondrosarcoma models included cell cycle, DNA damage response, and DNA damage checkpoint signal transduction, suggesting that the DNA damage response may be inhibited." (PMID 40188944, 2025). "Recently, a meta-analysis study utilized individual patient data to analyze the clinical and prognostic association of IDH1/2 mutations in chondrosarcoma patients compared to those without mutations." (PMID 40288045, 2025). "The most representative group consisted of patients with chondrosarcoma, but the small number of chondroma cases did not allow for a definite conclusion about the IDH1/2 mutational landscape in this benign tumor with a rare intracranial localization." (PMID 38248076, 2024). "To explore whether depletion of mutant IDH sensitizes chondrosarcoma cells to compounds from our drug screening library, we performed a drug sensitivity analysis in mutant IDH1 KO clones (J14 and H2), comparing their responses with those of the parental cells." (PMID 39684713, 2024).
chondrosarcoma (continued). "Integrated methylation and gene expression analysis revealed distinct IDH1/IDH2-associated methylation and transcriptional profiles as early events in DDCS, which may underlie the pathogenesis of dedifferentiation in chondrosarcomas." (PMID 36926116, 2023). "Interestingly, mutations in the IDH1 and IDH2 genes are found in 50–70% of chondrosarcomas and are implicated in chondrosarcoma tumorigenesis." (PMID 37048590, 2023). "The three chondrosarcomas of patients with Ollier syndrome (100%) harbored a mutation of IDH1, and all 3 cases shared the same mutation: R132C(TGT); none of the patients presented IDH2 mutation." (PMID 37752419, 2023). "Mutations in the IDH1 and IDH2 genes were shown to cause vulnerability to PARP inhibition in other cancer types; however, talazoparib showed variable sensitivity in a panel of conventionally cultured chondrosarcoma cell lines." (PMID 36729612, 2023). "De Andrea, San-Julian, and Bovée, (19 in an analysis of cartilaginous tumors of the bone, verified that the molecular alterations can be used for the diagnosis include alterations of IDH1 (R132C; R132H) in enchondromas, conventional chondrosarcomas, and undifferentiated chondrosarcoma." (PMID 37469494, 2023). "Considering that no subsequent shared genetic events were identified in the chondrosarcoma from our limited analyses, it is critical to conduct a further comprehensive investigation to discover IDH1-associated tumorigenesis." (PMID 35765075, 2022). "For the first time, we conducted whole-exome sequencing of germline DNA and chondrosarcoma tissue in MS patient, revealing IDH1 R132C somatic mutation in chondrosarcoma lesions but not in blood DNA." (PMID 35765075, 2022). "Mutations in IDH were first reported in colon cancers; however, several studies have now reported mutations in IDH1 and IDH2 in several cancers, including gliomas, intrahepatic acute myeloid leukemia, and chondrosarcoma." (PMID 36160383, 2022). "Our case revealed that the IDH1 R132C mutation was only present in the ankle chondrosarcoma tissue but not in the blood of this patient, and the presence of the mutation in the enchondroma/hemangioma tissue of the patient remains to be confirmed." (PMID 35765075, 2022). "A phase I multicenter clinical trial investigating the mutant IDH1 inhibitor ivosidenib (AG-120) in twenty-one patients with advanced chondrosarcoma demonstrated safety with minimal toxicity and a median progression free survival (PFS) of 5.6 months with a PFS rate of 39.5% at 6 months." (PMID 34938658, 2021). "In summary, we demonstrated the distinct characteristics of chondrosarcoma patients harboring IDH1/2 mutations as compared with patients without these mutations." (PMID 34085407, 2021). "Our meta‐analysis demonstrated the distinct characteristics of IDH1/2‐mutated chondrosarcomas in comparison to those without mutations." (PMID 34085407, 2021). "To this end, we selected several IDH1/2-WT and -mutant cholangiocarcinoma, fibrosarcoma and chondrosarcoma cell lines, and we first tested monotherapy PARP and ATR inhibitor sensitivity in order to identify the appropriate dose ranges for the combination drug studies." (PMID 34027408, 2021). "Considering G3 conventional chondrosarcomas, EPHA2 expression was lower in the IDH1-mutated samples when compared to the IDH1 wild-type samples (* p < 0.05), while the opposite was observed with respect to the IDH2 mutations (higher EPHA2 expression in IDH2-mutated samples; * p < 0.05)." (PMID 34831119, 2021). "Finally, chondrosarcomas display different grades of aggressiveness, which affect, for example, the IDH1/2 dependency of these tumors." (PMID 34831119, 2021). "The TCGCA does not include chondrosarcoma but IDH1 mutations have been associated with suppressed immune response pathways based on bioinformatics analyses of TCGA transcriptomic datasets." (PMID 34938658, 2021).
chondrosarcoma (continued). "IDH1 and IDH2 mutated chondrosarcomas have a distinct metabolomic profile with increased lactate, the TCA intermediates succinate, fumarate, and malate, amino acids broadly and acylcarnitines compared to non-mutated cancer cells based on patient derived xenografts." (PMID 34938658, 2021). "Since not all chondrosarcomas harbour IDH1/2 mutations, the finding of wild-type IDH1/2 does not exclude chondrosarcoma." (PMID 31838586, 2020). "IDH-1 inhibitors are showing promising activity in IDH-1 mutant chondrosarcomas." (PMID 32707689, 2020). "The finding of convincing tumour osteoid distinguishes chondroblastic osteosarcoma from chondrosarcoma; additional testing for IDH1/2 may be helpful to differentiate." (PMID 31838586, 2020). "However, IDH1/IDH2 mutations were found to be associated with longer relapse-free survival and metastasis-free survival in high-grade chondrosarcomas." (PMID 32295254, 2020). "The chondrosarcoma tumors were then excised and analyzed for IDH1 expression." (PMID 31935911, 2020). "Genetically, two main groups of chondrosarcomas exist: central chondrosarcomas, characterized by mutations in the isocitrate dehydrogenase genes IDH1 and IDH2, and secondary peripheral chondrosarcomas, characterized by alterations in the exostosin glycosyltransferase 1 (EXT1) and 2 (EXT2) genes." (PMID 32295254, 2020). "Targeting glutaminolysis with CB-839, metformin, phenformin or chloroquine is a potential therapeutic strategy for a subset of high-grade chondrosarcomas, irrespective of the presence or absence of an IDH1/2 mutation." (PMID 29576625, 2018). "High-grade chondrosarcomas are dependent on glutaminolysis which is independent of IDH1/2 mutation status." (PMID 29576625, 2018). "In summary, in central chondrosarcoma IDH1 or -2 mutations do not affect immunohistochemical levels of 5-hmC, 5mC, trimethylation of H3K4, -K9 and K27 and outcome, as compared to wildtype." (PMID 28484589, 2017). "No detectable level of IDH1/2 gene mutations was found in either P1-S1 or P1-S2, which is consistent with previous research demonstrating that not all chondrosarcomas harbor such mutations." (PMID 27248819, 2016). "Our aim is to determine whether mutant IDH1 inhibitor AGI-5198 exposure alters the tumor phenotype or D-2HG production in IDH1-mutant human chondrosarcoma cell lines." (PMID 26368816, 2015). "The high prevalence of IDH1/2 mutations in enchondroma and chondrosarcoma suggest a causal rather than a bystander role." (PMID 25895133, 2015). "On the other hand, HT1080, formally derived from a “fibrosarcoma of bone” but in retrospect presumably representing dedifferentiated chondrosarcoma based on its IDH1 mutation, showed no alterations in gene expression, nor in CpG island methylation levels." (PMID 25895133, 2015). "Central conventional chondrosarcomas carry mutations in IDH1 or IDH2 in 38–70% of primary central chondrosarcomas (arising without a preexisting benign enchondroma) and in 86% of the secondary central chondrosarcomas." (PMID 26046462, 2015). "Additionally, the migration of these cells was significantly altered, suggesting that inhibition of mutant IDH1 is clearly disrupting chondrosarcoma cell physiology." (PMID 26368816, 2015). "Thus, monotherapy based on inhibition of mutant IDH1 appears insufficient for treatment of inoperable or metastasized chondrosarcoma patients." (PMID 25895133, 2015). "Our results suggest that while mutations in IDH1 or-2 are an early event in tumorigenesis, chondrosarcoma is not dependent on mutant IDH1 anymore." (PMID 25895133, 2015).
chondrosarcoma (continued). "The high prevalence of IDH1 or -2 mutations in enchondroma and chondrosarcoma, suggesting a causal rather than a bystander role in tumorigenesis, led us to investigate the function of these mutations in chondrosarcoma." (PMID 25895133, 2015). "Our results suggest that mutations in IDH1/2, while being essential as an early event in the development of benign enchondroma, are not essential anymore after progression towards high grade chondrosarcoma." (PMID 25895133, 2015). "With evidence of AGI-5198 decreasing D-2HG production and suppressing the mutant IDH1 enzyme activity in chondrosarcoma cells, we next assessed whether this translated into inhibition of cell growth and tumorigenic activity." (PMID 26368816, 2015). "This panel can be implemented in studies ascertaining human chondrosarcoma tumorigenesis, should provide useful tools in the ongoing search for new targeted therapies, and aid in expanding our knowledge on the role of IDH1 and IDH2 mutations in chondrosarcoma formation." (PMID 22928481, 2012). "Ivosidenib—IDH1 inhibitor, commonly mentioned regarding novel CS therapies—showed disease control in IDH1-mutant conventional chondrosarcoma in Phase I (DCR 73.5%, median PFS 5.6 months), but MCS seldom harbours IDH1 mutations and may require alternative therapeutic approaches." (PMID 41294677, 2025). "This efficacy could be biased by the general indolent behavior of IDH1mut tumors compared to wild-type IDH1 tumors, but retrospective studies had not clearly defined if the IDH1 mutation could have a prognostic role in chondrosarcomas." (PMID 39123479, 2024). "Indeed, IDH1/2 mutations are frequent in dedifferentiated chondrosarcoma, while they are absent in UPSb and osteosarcoma." (PMID 38397231, 2024). "In addition, the whole exon analysis results revealed isocitrate dehydrogenase 1 (IDH1) R132C mutation in chondrosarcoma lesions but not in blood DNA." (PMID 35765075, 2022). "Since 49–61% of chondrosarcomas harbour an IDH1/2 mutation, additional mutation testing can be helpful to distinguish between these differential diagnoses in which the finding of an IDH1/2 mutation is diagnostic for chondrosarcoma and excludes chondroblastic osteosarcoma." (PMID 31838586, 2020). "Thus, mutations in Isocitrate Dehydrogenase-1 (IDH1) and -2 (IDH2) are found in 87% of enchondromas, up to 70% of conventional central chondrosarcomas and 54% of dedifferentiated chondrosarcomas and may drive sarcomagenic processes." (PMID 30987403, 2019). "We could therefore not confirm the prevailing hypothesis that IDH1/2 mutant chondrosarcoma cells rely on glutaminolysis to generate sufficient α-KG for D-2-HG production, as it seems that also high-grade chondrosarcomas that are wildtype for IDH1/2 depend on glutaminolysis." (PMID 29576625, 2018). "However, the use of such a mutant IDH1 inhibitor (AGI-5198) decreased D-2-HG levels in a dose dependent manner in three chondrosarcoma cell lines with endogenous IDH1 mutations, whereas proliferation and migration were not affected." (PMID 26046462, 2015). "Thus, while IDH1/2 mutations cause enchondroma, malignant progression towards central chondrosarcoma renders chondrosarcoma growth independent of these mutations." (PMID 25895133, 2015). "Thus, we hypothesized that D-2HG could be similarly measured in IDH1-mutant human chondrosarcoma cells, and would serve as a biomarker for tumor cell activity." (PMID 26368816, 2015). "Thus, other events are likely to be involved in chondrosarcoma progression, in which the mutation in IDH1 or -2 no longer seems to be a driver mutation." (PMID 25895133, 2015). "It is tempting to speculate that HT1080 obtained many additional molecular alterations upon dedifferentiation (i.e. fibrosarcomatous change in conventional chondrosarcoma) and prolongation in culture, thereby rendering the IDH1 mutation non-essential." (PMID 25895133, 2015).
chondrosarcoma (continued). "In our study, IDH1 and IDH2 mutant cases were combined for outcome analysis due to a small number of IDH2 mutant chondrosarcomas in our series." (PMID 38254737, 2024). "The analysis of IDH1 in patients with chondrosarcoma is an essential topic, and the literature shows results that indicate the need for more prospective and comparative studies identifying factors and treatments that may influence the survival of patients with chondrosarcoma." (PMID 37469494, 2023). "We used the chondrosarcoma JJ012 cell line and its derived CRISPR/Cas9 mutant IDH1 (IDH1mut) knockout (KO) cells." (PMID 35198082, 2022). "Individual Val and Leu/Ile levels were significantly elevated in mutant IDH1 chondrosarcomas and trended to increase in mutant IDH2 chondrosarcomas." (PMID 33762012, 2021). "Gln levels trended to increase by 2.8-fold in mutant IDH1 chondrosarcomas and achieved statistical significance in mutant IDH2 chondrosarcomas." (PMID 33762012, 2021). "13C α-KG labeling was reduced at 6 h in mutant IDH1 and IDH2 chondrosarcoma cells based on measurements of citrate (M2) and pyruvate (M3) labeling." (PMID 33762012, 2021). "Its inability to control tumor growth in chondrosarcoma may reflect the negative impact of the suppressive tumor microenvironment, especially since in colorectal cancer an association has been found between B7-H3 and IDH1 expression level." (PMID 33912442, 2021). "The combination of the histone deacetylase inhibitor, SAHA (suberoylanilide hydroxamic acid), and the DNA hypomethylating agent decitabine was tested on chondrosarcoma IDH wild type, IDH1 mutant and IDH2 mutant cell lines in vitro and in vivo." (PMID 32707689, 2020). "On the other hand, in vitro studies on several chondrosarcoma cell lines demonstrated that the effect of talazoparib is not dependent on the IDH1/2 status." (PMID 39334838, 2024). "The main difference between these two chondroid neoplasms is that IDH1 and IDH2 mutations, which are frequently found in chondrosarcomas, are not detected in chordomas." (PMID 38248076, 2024). "Immunohistochemical analysis using IDH1 and Ki67 markers in patients with chondrosarcoma is not useful for prognostic guidance." (PMID 37469494, 2023). "Immunohistochemical analysis using IDH1 and Ki67 markers in patients with conventional chondrosarcoma is not useful for prognostic guidance.Level of Evidence II, Prognostic Assessment, Results of Immunohistochemical Tests and Correlation with Survival." (PMID 37469494, 2023). "Because of the small sample size with available survival data when dividing into different subgroups, we did not found any associations of IDH1/2 mutations with patient RFS, MFS, and OS using the Cox proportional hazards model in other chondrosarcoma grades." (PMID 34085407, 2021). "From this analysis, we found medium- and long-chain lipid-derived acylcarnitines, C10, C16, and C16:1-OH/C14:1-DC significantly elevated in mutant IDH1 chondrosarcomas compared with non-mutant chondrosarcomas." (PMID 33762012, 2021). "Although amino acid profiles of mutant IDH chondrosarcomas clustered together, two mutant IDH1 tumors clustered closely to the non-mutant cluster group." (PMID 33762012, 2021). "To further confirm that it is the loss of IDH1mut rather than that of IDH1wt is responsible for the attenuated tumorigenicity of chondrosarcoma cells, we restored wild-type IDH1 expression in JJ012 and HT1080 IDH1 KO cells through the introduction of lentiviral vectors expressing Flag-tagged IDH1wt." (PMID 31935911, 2020). "In contrast to these findings in other tumour types, we showed previously that inhibition of mutant IDH1 in chondrosarcoma cell lines did not alter trimethylation of H3K4, H3K9 and H3K27, which is in concordance with the present immunohistochemical results." (PMID 28484589, 2017).